AR (androgen receptor)
Diseases named in the same sentence as AR in open-access papers (continued):
Sharing a sentence is not in itself a finding about the gene and the disease.
prostate carcinoma (continued). "In addition, tissue-specific highly expressed eRNAs, such as CCAT1 in colorectal cancer and androgen receptor (AR)-induced Kallikrein-related peptidase 3 (KLK3) eRNA (KLK3e) in prostate cancer, are considered new targets for treating various cancers." (PMID 35039581, 2022). "Targeting AR signaling has been widely applied for the therapy of prostate cancer." (PMID 36235203, 2022). "This is especially important in the context of prostate diseases, mainly prostate cancer, in which AR is an important therapeutic target because the expression of genes related to tumor cell proliferation and cell proliferation in BPH are controlled through this receptor." (PMID 35055079, 2022). "However, patients treated with ADT or AR targeted therapy are inevitably developing into castration‐resistant prostate cancer (CRPC) or becoming drug resistance." (PMID 36169095, 2022). "To examine whether ACK1 activation correlated with AR K609 acetylation in prostate cancer progression to metastatic stage, we performed tissue microarray analysis of clinically annotated prostate tumor samples." (PMID 35704598, 2022). "Prostate cancer (PCa) relies in part on AR-signaling for disease development and progression." (PMID 36078112, 2022). "Our findings indicated that, in pathology-confirmed prostate cancer with neuroendocrine differentiation, AR still expressed and functioned in a considerable part of the tumor; loss of AR expression was associated with adverse clinical stage and poor cancer cell differentiation." (PMID 36033483, 2022). "Furthermore, inhibitors of BCL-2 were more effective in treating prostate cancer NE than AR-positive prostate cancer." (PMID 36643868, 2022). "Given that IL-6 is exclusively produced in CAFs and not resting fibroblasts, it has been suggested that CAF-derived IL-6 may stimulate VEGF secretion from prostate cancer cells independently of AR signaling via PI3K/AKT, STAT3 and MAPK signaling." (PMID 36671452, 2022). "In this regard, it is important to understand the relationship between distinctive metabolic features, androgen receptor signaling, genetic drivers in prostate cancer, and the tumor microenvironment (symbiotic and competitive metabolic interactions) to identify metabolic vulnerabilities." (PMID 36358940, 2022). "The hormone binding initiates AR translocation into the nucleus followed by binding of the transcription factor to androgen response elements (AREs) and regulation of AR target genes, which play a crucial role in the growth, recurrence and metastasis of prostate cancer (PCa)." (PMID 36139361, 2022). "The current research and application of AR are mainly in prostate cancer and breast cancer." (PMID 36148010, 2022). "Recently, several international clinical trials have established the therapeutic efficacy of second-generation hormone therapy in prostate cancer, including abiraterone as an androgen synthesis inhibitor and enzalutamide as an androgen receptor (AR) antagonist." (PMID 35330713, 2022). "Moreover, CAPE inhibited not only AR activity but also proliferation and invasion in AR-positive and AR-negative prostate carcinoma cells, consistent with previous reports." (PMID 35053438, 2022). "Previously published proteomic studies analyzing the impact of AR antagonists on prostate cancer cell lines mainly focused on early, first-generation compounds and used two-dimensional gel electrophoresis, so that far fewer proteins were analyzed than in the present study." (PMID 36611998, 2022). "We further assessed whether IDA affects AR expression and DNA damage in enzalutamide-resistant prostate cancer cells and their parental cell lines." (PMID 36509750, 2022). "Our in vivo data argue that GZ17-6.02 may have single agent potential to suppress the growth of AR+ prostate cancer tumors and prolong survival." (PMID 36408163, 2022).
prostate carcinoma (continued). "TMPRSS2 is part of the type 2 transmembrane serine protease (TTSP) family and has been extensively studied in the context of prostate cancer as its expression is regulated in response to androgens through direct transcriptional regulation by the androgen receptor (AR)." (PMID 36560732, 2022). "Importantly, AR variants such as AR-v7 and ARv567es arise from intricate AR genomic arrangements and dysregulation of AS factors, and have been shown to be constitutively active in CRPC patients and prostate cancer cell models." (PMID 35864113, 2022). "Thus, it appears that SWI/SNF activity plays an important role in prostate cancer progression during both AR-dependent disease stages and ARSI-refractory disease stages." (PMID 36212399, 2022). "Perhaps highly inflamed prostate tissues spawn prostate cancers less likely to contain rearrangements involving AR target genes, a hypothesis and correlation that should be tested." (PMID 35104804, 2022). "Androgen receptor (AR) is the major player in initiating and promoting prostate cancer (PCa)." (PMID 36564767, 2022). "Interestingly, a recent study has found that MYB interaction with AR can sustain its ligand-independent activation and promote castration resistance in prostate cancer." (PMID 35864113, 2022). "Thus, we provide scientific evidence that apigetrin exerts anti-cancer potential via inhibiting AKT, a key transmitter of HIF-1α and AR signaling in prostate cancer cells." (PMID 35740392, 2022). "Thus, using drugs to target the AR pathway is a front-line treatment for patients with prostate cancer." (PMID 36446767, 2022). "Cyproterone acetate (CPA) is a synthetic steroid that was initially used in the treatment of prostate cancer because it could block androgen receptor (AR) and reduce serum testosterone levels." (PMID 36015177, 2022). "Additionally, LSD1 inhibitors have been shown to affect enhancer activity in various tumors, such as androgen receptor function in prostate cancer and ERα activity in breast cancer." (PMID 35514959, 2022). "For example, AU-15330 induced a potent inhibitor of tumor growth in xenograft models of prostate cancer, and synergized with the androgen receptor antagonist enzalutamide, even inducing disease remission in castration-resistant prostate cancer models without toxicity." (PMID 35409155, 2022). "This increased vulnerability may rely on the higher dependency on splicing of cancer cells with increased transcriptional activity, such as MYC-driven tumors and tumors displaying addiction to oncogenic transcription factors, such as the AR in prostate cancer." (PMID 35406598, 2022). "A 16 AR target gene signature that predicts recurrent prostate cancer and CRPC was, thus, proposed." (PMID 35682963, 2022). "Furthermore, androgens were known to regulate transient receptor potential melastatin 8 (TRPM8) protein expression through AR activation in prostate cancer development, and TRPM8 activity was reported to suppress prostate cancer cell migration." (PMID 37435453, 2022). "For example, SUMOylated AR has also been reported in both breast and prostate cancer using PLA." (PMID 37435453, 2022). "It has been found in prostate cancer studies that IL-23 produced by MDSCs can promote the development of prostate cancer through activating androgen receptor pathways in castration-resistant prostate cancer (CRPC), promoting cell survival and proliferation in androgen deficiency." (PMID 36131911, 2022). "Therefore, AR-targeting therapies are a mainstay of prostate cancer treatment based primarily on the observed effects on cell growth, resistance to treatment, and metastasis in malignant epithelial cells." (PMID 35885510, 2022). "Combined, these data show that CHST11 is an AR-repressed gene in prostate cancer." (PMID 35963852, 2022).
prostate carcinoma (continued). "Androgen deprivation therapy (ADT), which is used to block AR or eliminate AR ligands, initially works to inhibit the growth of prostate cancers as a frontline treatment, but over time castrate-resistant prostate cancer (CRPC) occurs through loss of ADT sensitivity." (PMID 35884386, 2022). "We previously reported the systematic reprogramming of the AR cistrome during both transformation from normal prostate epithelium to prostate cancer and during progression from localized prostate tumors to metastatic castration-resistant prostate cancer (mCRPC)." (PMID 35509021, 2022). "The growth of prostate cancer is largely dependent on activation of AR." (PMID 34057812, 2022). "Thus, our study provides a better understanding of AR signaling in the cellular plasticity of prostate cancer with neuroendocrine differentiation and allows new insights into the therapeutic development." (PMID 36033483, 2022). "Inhibition of the androgen receptor (AR) remains the mainstay treatment for prostate cancer." (PMID 35053548, 2022). "In a prostate cancer study, TLE3 deficiency was linked to resistance to AR inhibitors." (PMID 36438567, 2022). "However, in a significant number of cases, resistance to AR-targeted therapies arises; therefore, there is a need to discover new ways to treat prostate cancer." (PMID 35708495, 2022). "A study showed that berberine inhibited cell proliferation and triggered cell apoptosis of 22RV1 prostate cancer cells, and downregulated the expression of androgen receptor (AR), prostate-specific antigen (PSA), COX-2 and Bcl-2, and subsequently inhibited xenograft tumor growth in vivo." (PMID 35889396, 2022). "AR is a key transcription factor involved in androgen-dependent prostate cancer growth." (PMID 35800367, 2022). "Androgen deprivation therapy (ADT) is the most common non-surgical initial treatment for recurrent and treatment-naïve metastatic prostate cancer due to the universal and pivotal roles of androgens and androgen receptor (AR) in prostate growth and development and early stage prostate cancers." (PMID 35493092, 2022). "Our understanding of AR action has predominantly come from studies that have investigated the receptor’s role in the prostate, a small secretory gland at the base of the bladder, and prostate cancer." (PMID 36560732, 2022). "However, the roles of TR3 in androgen receptor (AR) expression and signaling in prostate cancer cells are poorly understood." (PMID 35454821, 2022). "In contrast, PKA signaling enhances the transcription of AR in prostate cancer cells." (PMID 36272644, 2022). "Furthermore, EGCG induced chemosensitization in all stages of breast and prostate cancer, by receptor-mediated mechanisms; indeed, it antagonized androgen action and decreased androgen receptor (AR) expression in hormone-responsive prostate cancer cells." (PMID 35956325, 2022). "In prostate cancer, PDOs with androgen receptor gene amplification were exquisitely and specifically sensitive to enzalutamide (androgen receptor antagonist), whereas those harboring both PTEN loss and PIK3R1 mutation were sensitive to PI3K pathway inhibitors (Everolimus and BKM-120)." (PMID 36077628, 2022). "In prostate cancer, AR–GR crosstalk also occurs extensively." (PMID 35761157, 2022). "The androgen receptor pathway is a key driver of prostate cancer progression." (PMID 35454866, 2022). "HDACs are necessary for functional AR signaling in prostate cancers, and HDAC inhibitors such as vorinostat and panobinostat blocked AR function by reducing AR expression and inhibiting coactivator/RNA polymerase II complex formation after AR binding to its DNA target element." (PMID 35582529, 2022). "Similar to other members of the nucleus receptor superfamily, the transcription factor activation of AR is modulated by cofactors or coregulators, and the interaction between AR and its cofactors plays important roles in the transformation and maintenance of prostate carcinoma." (PMID 35444697, 2022).
prostate carcinoma (continued). "However, the overexpression of PyK2 and phosphorylation of the androgen receptor increased the growth of prostate cancer cells." (PMID 36555115, 2022). "In the clinical study, PSA and AR ability were used to detect prostate cancer patients." (PMID 36443669, 2022). "A member of the fibroblast growth factor (FGF) family could interact with miRNA-541 to suppress androgen receptor signals in prostate cancer." (PMID 35741355, 2022). "The AR is involved in various disorders, including androgen insensitivity syndrome, spinal bulbar muscular atrophy, hypogonadism, benign prostatic hyperplasia, and prostate cancer (PCa)." (PMID 35723327, 2022). "Since biallelic loss of tumor suppressor genes in ctDNA is not specific to AR-independent prostate cancer, recent efforts have focused on using epigenomic techniques to improve NEPC detection." (PMID 36439451, 2022). "Although darolutamide and proxalutamide show clinical efficacy in CRPC patients harboring point mutations within the AR LBD, these antagonists cannot target AR variants such as AR-v7 or ARv567es that lack the LBD and contribute to prostate cancer progression and resistance to AR antagonists." (PMID 35864113, 2022). "This is the first study showing that HC-1119 may be used to treat other types of AR-positive cancers such as AR-positive TNBC in addition to the prostate cancer." (PMID 35960413, 2022). "Therefore, available studies strongly indicate the presence of AhR/AR crosstalk in prostate cancer cells, as various AhR ligands were reported to inhibit prostate cancer development, probably through several different mechanisms." (PMID 36613955, 2022). "Moreover, PROTAC 8 induced cell cycle arrest at the G0/G1 phase and apoptosis in AR-positive prostate cancer by downregulation of the protein levels of AR, PSA, and c-Myc as well as transcriptionally suppressed AR-regulated genes." (PMID 35702740, 2022). "Furthermore, the interaction of OTUD6A with Brg1 and AR was also verified in other prostate cancer cell lines, including PC-3, LNCaP, and C4-2 cells, through IP-IB analysis." (PMID 35233061, 2022). "Generally, the link between AR and NF-κB seems complex, as other proteins that are important in prostate cancer may also be involved in a crosstalk between these transcription factors." (PMID 36551650, 2022). "Therefore, as malignant transformation occurs, antiandrogen therapy is administered and AR signaling diminished, prostate cancer cells frequently show increased plasma membrane PSMA expression." (PMID 35086953, 2022). "Nevertheless, there is still a possibility that the LIFR‐K620ac/AKT pathway could influence AR signalling or be involved in castration resistant prostate cancer, but additional studies are needed in the future to address this." (PMID 35172032, 2022). "In, line with this, SETD7 methylation of estrogen and androgen receptor enhances their transcriptional activity, so future studies to identify its function in breast and prostate cancer could provide novel insights to treat endocrine-resistant cases." (PMID 35326563, 2022). "Androgen replacement via testosterone stimulation of castrated mice secondary to prostate cancer xenografts caused an increase in IGFBP5, indicating IGFBP5 may be regulated by the androgen receptor (AR) in some cases." (PMID 36465383, 2022). "AR is undeniably one of the most critical drivers of all stages of prostate cancer development, progression and treatment resistance, and it has been the mainstay of prostate cancer treatment for decades." (PMID 35406480, 2022). "AR protein elimination by enhanced protein or mRNA degradation is a realistic solution for avoiding AR reactivation during androgen deprivation therapy in prostate cancers." (PMID 35372068, 2022). "The availability of selective AR inhibitors (e.g., bicalutamide, enzalutamide, apalutamide) approved for the treatment of prostate cancer might have, thus, potential to be translated to other endocrine cancers." (PMID 35563746, 2022).
prostate carcinoma (continued). "The long half-lives and high levels of enzalutamide and BMS-641988 in the CNS may induce seizures in a small proportion of prostate cancer patients, as these AR antagonists can competitively bind and inhibit GABA-α activity." (PMID 35864113, 2022). "PRNCR1 and PCGEM1 are highly expressed in aggressive prostate cancer and bind to AR successively." (PMID 35103065, 2022). "The androgen receptor (AR) plays a central role in prostate cancer." (PMID 34986150, 2022). "The androgen receptor (AR) signaling pathway regulates the progression of prostate cancer (PC)." (PMID 37435458, 2022). "EGCG suppressed prostate cancer cell growth by modulating acetylation of androgen receptor." (PMID 36139145, 2022). "Besides dysregulating heat shock protein and suppressing AR expression in prostate cancer cells, enzalutamide can directly induce cell apoptosis." (PMID 36235203, 2022). "Bicalutamide and enzalutamide are FDA-approved AR antagonists for prostate cancer treatment." (PMID 35768871, 2022). "Notably, a recent study identified higher levels of mitochondrial malate dehydrogenase, MDH2, in AR-responsive prostate cancer." (PMID 35406510, 2022). "It is reported that a series of tsRNAs are responsive to sex hormones and are elevated in ER-positive BC and AR-positive prostate cancer, designating these tsRNAs as sex-hormone-dependent tRNA-derived RNAs (SHOT-RNAs) which are cleaved by ANG, forming 5′-SHOT-RNAs and 3′-SHOT-RNAs." (PMID 36072340, 2022). "Among these several actions, calcitriol exerts a role in WNT–β-catenin signalling in colon cancer, in estrogens synthesis and signalling in estrogen receptor-positive (ER+) postmenopausal breast cancer, and, moreover, in androgen receptor (AR) signalling in prostate cancer." (PMID 35741675, 2022). "Moreover, CAPE attenuated androgen-induced PSA and MALT1 expressions in AR-positive prostate carcinoma cells (LNCaP and 22Rv1)." (PMID 35053438, 2022). "The androgen receptor (AR) signaling axis is the major therapeutic target in prostate cancer (PC)." (PMID 36497382, 2022). "Summary of AR-targeted therapeutic agents for prostate cancers." (PMID 35372068, 2022). "Thus, it seems that an adaptation of prostate cancer to inhibition of AR signaling constitutes a vulnerability to SPA." (PMID 36194476, 2022). "Indeed, AR itself has been found to promote prostate cancer growth yet to suppress prostate cancer metastasis, two seemingly opposite characteristics associated with tumor progression." (PMID 36397101, 2022). "Our previous study shows that eNOS exhibits a significant upregulation in clinical CRPC tissues and several in vitro and in vivo models of CRPC, and increased NO production can contribute to the antiandrogen resistance in prostate cancer cells via its suppression of AR activity." (PMID 35526071, 2022). "Thus, in contrast to phospho-acetyl switch that inhibits STAT1 transcription activity upon its acetylation, AR seems to use both the modifications to allow prostate cancer to evolve through progressive stages to become CRPC." (PMID 35704598, 2022). "The NAA10–AR (androgen receptor) axis is essential for prostate cancer cell growth." (PMID 35669725, 2022). "The most highlighted keywords were “androgen receptor” (n = 1,209), “breast cancer” (n = 690), “expression” (n = 545), “breast cancer” (n = 410), “prostate cancer” (n = 290), and so on, revealing the trend from molecular mechanism level to therapeutic use level." (PMID 35800434, 2022). "Interestingly, selective inhibitors against p300/CBP, namely CCS1477 has been shown to inhibit the AR transcription program and is currently being evaluated in clinical trials for metastatic castration resistance prostate cancer (NCT03568656)." (PMID 35774123, 2022). "Our data support the use of GZ17-6.02 as a therapeutic agent in patients with AR+ prostate cancer." (PMID 36408163, 2022).